CCNA2 (cyclin A2)
Description:
Essential for the control of the cell cycle at G1/S and G2/M transition. Functions through the formation of specific serine/threonine protein kinase holoenzyme complexes with the cyclin-dependent protein kinases CDK1 or CDK2. The cyclin subunit confers the substrate specificity of these complexes and differentially interacts with and activates CDK1 and CDK2 throughout the cell cycle.
Synonyms: CCN1; CCNA
Tractability: Small molecule: a structure with a bound ligand is known; a high-quality ligand is known; it belongs to a druggable protein family. PROTAC: UniProt records ubiquitination sites on it; ubiquitination databases record sites on it; a small molecule that binds it is known.
Target class: Other cytosolic protein
Gene: Protein-coding gene on chromosome 4 (121,816,444 to 121,823,917, reverse strand). Ensembl gene ENSG00000145386.
Subcellular location: Nucleus; Cytoplasm
Subcellular location (Human Protein Atlas): Cytosol; Nucleoplasm
Pathways (Reactome):
Cell Cycle: Cdc20:Phospho-APC/C mediated degradation of Cyclin A; Chk1/Chk2(Cds1) mediated inactivation of Cyclin B:Cdk1 complex; Cyclin A/B1/B2 associated events during G2/M transition; Cyclin A:Cdk2-associated events at S phase entry; G0 and Early G1; G2 Phase; G2/M DNA replication checkpoint; Regulation of APC/C activators between G1/S and early anaphase; SCF(Skp2)-mediated degradation of p27/p21; Telomere Extension By Telomerase; Transcription of E2F targets under negative control by p107 (RBL1) and p130 (RBL2) in complex with HDAC1
Cellular responses to stimuli: DNA Damage/Telomere Stress Induced Senescence; Senescence-Associated Secretory Phenotype (SASP)
DNA Replication: CDK-mediated phosphorylation and removal of Cdc6; Orc1 removal from chromatin
DNA Repair: Processing of DNA double-strand break ends
Metabolism of proteins: Ub-specific processing proteases
Gene Ontology:
Molecular function: cyclin-dependent protein serine/threonine kinase regulator activity; protein binding; protein domain specific binding; protein kinase binding
Biological process: cell cycle G1/S phase transition; G2/M transition of mitotic cell cycle; post-translational protein modification; Ras protein signal transduction; regulation of DNA replication; G1/S transition of mitotic cell cycle; animal organ regeneration; cellular response to cocaine; cellular response to estradiol stimulus; cellular response to hypoxia; cellular response to insulin-like growth factor stimulus; cellular response to leptin stimulus; cellular response to luteinizing hormone stimulus; cellular response to nitric oxide; cellular response to platelet-derived growth factor stimulus; cochlea development; mitotic cell cycle phase transition; positive regulation of DNA biosynthetic process; positive regulation of fibroblast proliferation; response to estradiol; response to glucagon
Cellular component: cyclin A2-CDK2 complex; cyclin-dependent protein kinase holoenzyme complex; cytoplasm; cytosol; nucleoplasm; nucleus; cyclin A2-CDK1 complex; microtubule organizing center; female pronucleus; male pronucleus
Genetic constraint (gnomAD): Loss-of-function variants: 3 observed, 42.27 expected, observed/expected ratio (o/e) 0.071, 90% interval 0.031 to 0.18. The upper end of that interval is the gene's LOEUF score, 0.18, which puts it in group 1 of 6, group 1 being the genes least tolerant of losing a copy. Missense variants: 348 observed, 503.02 expected, observed/expected ratio (o/e) 0.69, 90% interval 0.63 to 0.76. Synonymous variants: 199 observed, 194.9 expected, observed/expected ratio (o/e) 1.02, 90% interval 0.91 to 1.15.
Homologues: Orthologues: chimpanzee CCNA2 (99% identical), macaque CCNA2 (99% identical), pig CCNA2 (92% identical), dog CCNA2 (91% identical), rabbit CCNA2 (90% identical), guinea pig CCNA2 (88% identical), mouse Ccna2 (85% identical), rat Ccna2 (85% identical), tropical clawed frog ccna2 (60% identical), zebrafish ccna2 (60% identical), Drosophila melanogaster CycB (25% identical), Caenorhabditis elegans cyb-1 (23% identical), and 6 more. Paralogues in human: CCNA1 (46% identical), CCNB1 (28% identical), CCNB2 (27% identical), CCNB3 (25% identical), CCNF (23% identical), CCNO (20% identical), CCNE2 (19% identical), CCNE1 (19% identical), CCND3 (18% identical), CCNJ (18% identical), CCND2 (18% identical), CCND1 (17% identical), and 6 more.
Diseases named in the same sentence as CCNA2 in open-access papers:
CCNA2 is named in the same sentence as 198 diseases in open-access papers, as found by Europe PMC text mining. Sharing a sentence is not in itself a finding about the gene and the disease. The quoted sentences say what the papers report.
breast cancer (147 papers, 1998 to 2026). A primary or metastatic malignant neoplasm involving the breast. "Reduced survival in individuals with HCC and breast cancer is associated with abnormal expression of CCNA2." (PMID 39764737, 2025). "CCNA2 encodes Cyclin A2, which is a suppressor of intracellular oxidative stress that is upregulated in colorectal and breast cancer tissues and is associated with poor prognosis." (PMID 36133439, 2022). "By using the TCGA breast cancer dataset, two genes including CCNA2 and CCNB2 were identified to be associated with the PTTG1." (PMID 32272902, 2020). "It has also been found that CCNA2 is significantly associated with tamoxifen resistance in breast cancer patients." (PMID 31956366, 2020). "In this study, we identified 283 overlapping DEGs (105 up- and 178 down-regulated) and six hub genes (RRM2, CDC20, CCNB2, BUB1B, CDK1, CCNA2) associated with breast cancer tumorigenesis and progression based on multiple datasets." (PMID 33083112, 2020). "According to the PPI networks, five hub genes (TPX2, KIF2C, CDCA8, BUB1B, and CCNA2) were identified as key genes associated with breast cancer progression." (PMID 31285741, 2019). "Overall, we identified five genes (TPX2, KIF2C, CDCA8, BUB1B, and CCNA2) associated with distant metastasis, indicating these genes as potential biomarkers for assessing the risk of breast cancer recurrence and distant metastasis." (PMID 31285741, 2019). "Cyclin A2 overexpression is common in breast cancer and is associated with high propensity for epithelial-mesenchymal transition (EMT) and metastasis." (PMID 30038716, 2018). "Several studies have demonstrated that CCNA2 has significant power to predict the survival of breast cancer patients and it is also found that CCNA2 was closely associated with tamoxifen resistance." (PMID 29467930, 2018). "Our studies to address the consequence of loss of cyclin A2 in breast cancer cells identified that cyclin A2 deficiency causes high rates of DSBs in the cells." (PMID 29207607, 2017). "Specifically, CCNA2 overexpression is associated with poor distant metastasis survival in ER+ breast cancer cohorts GSE47561 (P = 5.057e−11) and Van dataset (and 8.093e−05)." (PMID 24622579, 2014). "Therefore, it appears that the proliferation proteins, Cyclin A2 and Ki-67, are associated with poor survival among African American breast cancer patients." (PMID 37273492, 2023). "Furthermore, it appears that the proliferation proteins, Cyclin A2 and Ki-67, are associated with poor survival among African American breast cancer patients." (PMID 37273492, 2023). "In addition, we demonstrated that decreased GATA3 levels are required for progestin-induced upregulation of cyclin A2, which mediates the G1 to S phase transition of the cell cycle and was reported to be associated with poor prognosis in breast cancer." (PMID 25479686, 2014). "Five hub genes (TPX2, KIF2C, CDCA8, BUB1B, and CCNA2) associated with the risk of distant metastasis were extracted for further research, which might be used as biomarkers to predict distant metastasis of breast cancer." (PMID 31285741, 2019). "To determine whether loss of cyclin A2 sufficiently perturbs HR to sensitize breast cancer cells to DNA crosslinkers and PARP inhibition, we treated the cells with DNA cross linker, cisplatin, and two PARP inhibitors, veliparib (ABT-888) and olaparib (AZD2281)." (PMID 29207607, 2017). "The aim of the present study, therefore, was to investigate whether cyclin A2 deficiency perturbs HR pathway in human breast cancer cells and to determine if its loss hypersensitizes the cells to DNA crosslinking agent, cisplatin, and PARP inhibitors, veliparib and olaparib." (PMID 29207607, 2017). "However, the association between CCNA2 overexpression and tamoxifen resistance in ER+ breast cancer remains unclear." (PMID 24622579, 2014). "In recent years, some studies confirmed that the expression of CCNA2 increased in breast cancer and ovarian cancer." (PMID 40345591, 2025).
breast cancer (continued). "PTENP1 also contributes to intra-S to G2/M phase arrest by targeting CDK2-cyclin A2 in breast cancer cells, suggesting its relevance in cell cycle regulation." (PMID 39125832, 2024). "CCNA2 belongs to the cell cyclin family and is an oncogene of various tumors, such as clear cell renal cell carcinoma and breast cancer." (PMID 38053725, 2023). "This, together with our demonstration of a negative correlation between gene expressions of E2F3, CDK2 and CCNA2 with IKBKB expression in breast cancer patients, implicates IKKβ in regulating cell cycle progression in cooperation with miR-125b." (PMID 38093346, 2023). "CCNA2, which was overexpressed in case of breast cancer and has an oncogenic role in cancer, participates in the tumorigenesis and metastasis of breast cancer." (PMID 36980449, 2023). "For the study, based on the available resources, we choose to follow the expert panel recommendations and the prognostic significance of Cyclin A2 and Ki-64 in breast cancer mainly in African American women which needs evaluation in larger studies." (PMID 37273492, 2023). "The aberrant expression of AURKA, BUB1B, CCNA2, CCNB2, and PBK resulted in a poorer survival rate of breast cancer patients in the high-risk group having a survival rate of less than 2 years." (PMID 36980449, 2023). "Previously, the connection between Ki-67 and other cell cycle genes was studied using bioinformatics, including a direct correlation between cyclin A2 and Ki-67 expression at both the mRNA and protein levels was found in breast cancer cell line." (PMID 37264344, 2023). "The other genetic alteration, i.e., amplification was related to an increased growth of breast cancer cells and further assisted in its metastasis due to the upregulation of the CCNA2 gene." (PMID 36980449, 2023). "Some articles showed that CCNA2 is a vital sign to judge the poor prognosis of the tumor, as it is also highly expressed in pancreatic cancer, breast cancer, lung cancer, and other tumors." (PMID 35999505, 2022). "Specifically, Nek5 was shown to enhance breast cancer cell mesenchymal morphology and migration, and was also shown to enhance breast cancer cell proliferation via upregulation of Cyclin A2 expression, while downregulating Cyclin D1, D3, and E1 expression." (PMID 35409400, 2022). "Immunohistochemical analysis showed significantly high level of CCNA2 was observed in the tissues from breast cancer patients compared to that from normal controls." (PMID 36439516, 2022). "The study found that CCNA2 expression was significantly high in carcinoma tissues than in normal controls, and CCNA2 was considered as a potential immunotherapy marker in breast cancer." (PMID 35906548, 2022). "CCNA2 and CCNB1 are prognostic markers for ER +ve breast cancer and are closely associated with hormone therapy resistance." (PMID 34981672, 2022). "In line with CCNA2, CCNB2 increased the risk of multiple cancer prognoses such as such as adrenocortical carcinoma, lung cancer, breast cancer, and colorectal adenocarcinoma." (PMID 33879165, 2021). "CCNA2 was also reported to be overexpressed in breast cancer and utilized as a prognostic biomarker for ER+ subtype." (PMID 33662042, 2021). "There is accumulating evidence demonstrating the correlation between CCNA2 and tumorigenesis of numerous cancers, including lung cancer, breast cancer, and pancreatic ductal carcinoma." (PMID 34603443, 2021). "In a breast cancer study, CCNA2 was found to be an effective prognostic marker for disease-free survival, overall survival and recurrence-free survival in estrogen receptor-positive breast cancer patients." (PMID 31956366, 2020). "In the current study, we obtained 283 overlapping DEGs and six hub genes (RRM2, CDC20, CCNB2, BUB1B, CDK1, and CCNA2) related to the occurrence and development of breast cancer via comprehensive bioinformatics analysis." (PMID 33083112, 2020).
breast cancer (continued). "CCNA2 was overexpressed in bladder cancer, ER+ breast cancer and related to tamoxifen resistance, hepatoma with promoting cell proliferation and lung adenocarcinoma." (PMID 33186389, 2020). "There were articles that showed that CCNA2 is an important sign to judge the poor prognosis of the tumor, as it also highly expressed in pancreatic cancer, breast cancer, lung cancer, and other tumors." (PMID 33519906, 2020). "Based on integrated bioinformatic analysis, the present study has identified 321 DEGs and six hub genes (CDK1, CCNA2, TOP2A, CCNB1, KIF11, and MELK) that are associated with breast cancer tumorigenesis and progression." (PMID 31428132, 2019). "CCNA2 is highly expressed in a variety of tumor types, such as lung cancer, breast cancer, cervical cancer, and liver cancer." (PMID 30995921, 2019). "CCNA2 functions as a key regulator of cell cycle and is reported to be up-regulated in many cancers including breast cancer." (PMID 31428132, 2019). "Five hub genes, including TPX2, KIF2C, CDCA8, BUB1B, and CCNA2, were validated to be notably associated with the shorter DMFS of breast cancer in the patient cohort based on KM Plotter." (PMID 31285741, 2019). "Together, these results suggest that cyclin A2 is a positive regulator of MRE11 in breast cancer cells." (PMID 29207607, 2017). "Taken together, our present study identifies cyclin A2 as a novel determinant of HR efficiency in human breast cancer cells." (PMID 29207607, 2017). "It was reported that Cyclin A2 (CCNA2) was significantly overexpressed in various cancer types including ER+ breast cancer, splenic diffuse red pulp small B-cell lymphoma, rectal neuroendocrine tumors." (PMID 28969025, 2017). "Collectively, these results show that cyclin A2 insufficiency disrupts HR repair in breast cancer cells." (PMID 29207607, 2017). "Ellagic acid induces cell cycle arrest at G0–G1 in human breast cancer MCF-7 cells mediated by a cyclin A2 and cyclin E2 downregulation and an upregulation of the CDK-inhibitors p21Cip1, p15 and p19." (PMID 29112149, 2017). "We demonstrate that cyclin A2 plays a vital role in maintaining adequate levels of MRE11 and RAD51 proteins for proper functioning of HR repair and that its loss sensitizes the breast cancer cells to DNA damaging agents and PARP inhibitors." (PMID 29207607, 2017). "Potential implications of cyclin A2 in breast cancer have been suggested, since transgenic mice overexpressing cyclin A2 generate aberrant nuclear abnormalities suggestive of preneoplasic alterations." (PMID 25479686, 2014). "Accordingly, cyclin A2 was found to be significantly downregulated in MDA-MB-231 breast cancer cells engineered to overexpress GATA3." (PMID 25479686, 2014). "Overall, we suggest that CCNA2 is a biomarker for the prognosis of ER+ breast cancer and monitoring of tamoxifen efficacy." (PMID 24622579, 2014). "Analysis of a publicly available microarray dataset showed that cyclin A2 was the only member of the cyclin family that was significantly downregulated upon GATA3 overexpression in MDA-MB-231 breast cancer cells." (PMID 25479686, 2014). "Our results show the significant prognostic power of CCNA2 in ER+ breast cancer progression and tamoxifen resistance." (PMID 24622579, 2014). "In this study, we demonstrated that CCNA2 had significant predictive power in distant metastasis free survival, disease free survival, recurrence free survival and overall survival of ER+ breast cancer patients." (PMID 24622579, 2014). "CCNA2, a key regulator of cell cycle, is overexpressed in many human cancers, including breast cancer." (PMID 24622579, 2014). "Restoration of miR-10b* expression by using mimic 10b* reduces PLK1, BUB1 and CCNA2 protein expression in diverse breast cancer cell lines." (PMID 23125021, 2012). "Here, we document that down-regulation of miR-10b* correlates with aberrant expression of PLK1, BUB1 and CCNA2 proteins in breast cancer specimens when compared to their matched peritumoural samples." (PMID 23125021, 2012).